FGF23 (fibroblast growth factor 23)
Diseases named in the same sentence as FGF23 in open-access papers (continued):
Sharing a sentence is not in itself a finding about the gene and the disease.
hypophosphatemia (continued). "Overproduction of fibroblast growth factor 23 (FGF23) by the tumor causes hypophosphatemia and consequently induces inappropriate bone turnover." (PMID 34797338, 2021). "Given persistent hypophosphatemia, FGF23 was checked, and levels returned strikingly elevated at 2,430 RU/mL (≤ 180 RU/mL) suggesting an FGF23 secreting tumor as the most likely cause for severe hypophosphatemia." (PMID 33191899, 2021). "A higher FGF23 due to hypophosphorylation resembles the GoF mutation, which can translate into hypophosphatemia, hypocalcemia, hyperphosphaturia, low 1,25(OH)2D3 and secondary osteomalacia/hypophosphatemic rickets." (PMID 34360805, 2021). "More than 300 distinct pathogenic variations have been reported, leading to FGF23 excess, hypophosphatemia and phosphaturia and inappropriately low levels of 1,25(OH)2D3." (PMID 34068220, 2021). "Human diseases associated with excessive intact circulating FGF23 (iFGF23) result in hypophosphatemia and low vitamin D hormone in patients with normal kidney function." (PMID 33989306, 2021). "Serum C‐terminal FGF23 level was tested based on concern for an acquired cause of hypophosphatemia such as TIO, and was within the reference range at 138 RU/mL (LabCorp ELISA 44–215; LabCorp, Burlington, NC, USA)." (PMID 33615107, 2021). "Several other genes, such as FGF23, DMP1, and ENPP1, are involved in the synthesis, signaling, and regulation of FGF23 and their mutations are responsible for hypophosphatemia; they account for less than 20% of the cases." (PMID 34421819, 2021). "Four days later, he was admitted to our department to examine the cause of FGF23-related hypophosphatemia." (PMID 34901334, 2021). "Anti-FGF-23 neutralizing antibody can increase the blood phosphorus and 1,25(OH)2D levels in hypophosphatemia (Hyp) young mice and improve humerus and X-linked hypophosphatemic rickets/osteomalacia (XLH) in young Hyp mice." (PMID 34650980, 2021). "Many medical disorders were described in which oversynthesis of FGF23 results in hypophosphatemia, i.e., X-linked familial rickets, autosomal dominant and recessive forms of hypophosphatemia, and tumour-induced osteomalacia." (PMID 34258392, 2021). "XLH is a chronic condition primarily characterized by elevated FGF23 levels, causing hypophosphatemia and inappropriately low or normal levels of 1,25-vitD." (PMID 34203792, 2021). "A possible cause of hypophosphatemia is paraneoplastic secretion of fibroblast growth factor 23 (FGF-23)." (PMID 31963334, 2020). "Excess FGF23 in both humans and mouse models causes hypophosphatemia, suppression of calcitriol levels and rickets (in childhood) or osteomalacia (during adulthood)." (PMID 33205007, 2020). "Conversely, excessively high levels of circulating Klotho are associated with hypophosphatemia and hypocalcemia, increased FGF23 production, bone rarefaction, osteomalacia and fractures." (PMID 32640692, 2020). "FGF23, fibroblast growth factor 23, possesses broad mitogenic and cell survival activities, and it is implicated in hypophosphatemia and diabetic nephropathy." (PMID 32993645, 2020). "FGF23 excess results in renal phosphate loss with subsequent hypophosphatemia, muscle weakness, and impaired mineralization." (PMID 31834957, 2020). "Loss of PHEX leads to the overproduction of FGF23 in osteocytes, causing hypophosphatemia with bone mineralization impairment, and thus bone fragility." (PMID 32982979, 2020). "All of these caused FGF23 related phosphaturia, hypophosphatemia, short stature, and bone deformities as in our cases." (PMID 31514490, 2020). "Hypophosphatemia after FCM treatment is caused by transiently rising plasma levels of the phosphaturic hormone intact FGF23 (iFGF23), which stimulates the renal excretion of phosphorus." (PMID 32654663, 2020). "The clinical phenotypes of the patients, such as high levels of intact circulating FGF23, hypophosphatemia, and severe genu varum, are consistent with the loss‐of‐function genotype of PHEX." (PMID 32511895, 2020).
hypophosphatemia (continued). "ADH mice had elevated intact Fgf23 levels and hypophosphatemia during iron deficiency, whereas wild‐type controls maintained normal serum intact Fgf23 and inorganic phosphate levels." (PMID 31834957, 2020). "Collectively, these results indicate that FGF23-induced hypophosphatemia is associated with muscle weakness in XLH." (PMID 30808384, 2019). "In adults with X‐linked hypophosphatemia (XLH), excess FGF23 impairs renal phosphate reabsorption and suppresses production of 1,25‐dihydroxyvitamin D, resulting in chronic hypophosphatemia and persistent osteomalacia." (PMID 31369697, 2019). "An excess of FGF23 activity has also been associated with a number of other conditions causing hypophosphatemia, including tumor‐induced osteomalacia, fibrous dysplasia of the bone, and cutaneous skeletal hypophosphatemia syndrome." (PMID 31485552, 2019). "He developed hypophosphatemia associated with elevated levels of fibroblast growth factor 23 (FGF‐23) and severe proximal muscle weakness." (PMID 31687644, 2019). "Both the hypophosphatemia and hyperphosphaturia were linked to increased fibroblast growth factor 23 (FGF23) concentrations." (PMID 30525344, 2019). "Tumor-induced osteomalacia is caused by tumors that secrete fibroblast growth factor 23 (FGF23), inducing hypophosphatemia, leading to a reduced osteoblast differentiation and matrix mineralization." (PMID 31035457, 2019). "The most common FGF23‐mediated hypophosphatemia is X‐linked hypophosphatemia (XLH), caused by mutations in the PHEX gene." (PMID 31485552, 2019). "X‐linked hypophosphatemia (XLH) is a disease caused by abnormally elevated FGF23 levels, which cause persistent hypophosphatemia accompanied by subsequent reduction in bone mineralization that presents as rickets or osteomalacia." (PMID 30828689, 2019). "Absence of dentin matrix protein 1 (DMP‐1) and phosphate‐regulating gene with homologies to endopeptidases on the X chromosome (PHEX) influences expression of FGF‐23 in bone and mutations in the encoding genes result in congenital hypophosphatemia." (PMID 31485552, 2019). "TIO is an interesting example of an FGF23-mediated hypophosphatemia, as this acquired disease is caused by FGF23-secreting tumours, whose total resection is completely curative." (PMID 30808384, 2019). "Inactivating mutations of FAM20C have been identified in patients with FGF23-related hypophosphatemia and dental abnormalities." (PMID 30972027, 2019). "From these results, high FGF23 in patients with chronic hypophosphatemia seemed to indicate that this hypophosphatemia is caused by excessive actions of FGF23." (PMID 29515522, 2018). "Recently there have been multiple reports of hypophosphatemia with the use of ferric carboxy-maltose for iron deficiency anemia and it appears to be related to acute and reversible increase in FGF-23 levels." (PMID 30109232, 2018). "ADHR is caused by uncontrolled FGF23 activity resulting in excessive renal phosphate loss, hypophosphatemia, very low levels of 1,25-dihydroxyvitanin D, osteomalacia, and rickets." (PMID 30087898, 2018). "And there is an alternative, unifying explanation that increases in FGF23 is the initial factor causing secondary downregulating of α-Klotho by hypophosphatemia or reduced 1,25D3." (PMID 30159331, 2018). "This led to the discovery that iron deficiency is an environmental trigger, which stimulates FGF23 expression and thus hypophosphatemia in ADHR." (PMID 29280738, 2017). "Increased renal phosphate loss and hypophosphatemia due to increased serum FGF23 levels have been reported in Raine’s syndrome." (PMID 29280738, 2017). "FAM20C can suppress FGF23 production by enhancing DMP1 expression and its inactivation causes FGF23-related hypophosphatemia by decreasing transcription of DMP1, resulting in increased FGF23 levels in patients with Raine’s syndrome." (PMID 29280738, 2017).
hypophosphatemia (continued). "Immediately after surgery, we noted a sharply decrease in serum level of FGF23, associated with an improved hypophosphatemia and a gradual relief of systematic pain that disappeared within two months of surgery." (PMID 28193220, 2017). "The high production of fibroblast growth factor 23 (FGF23) by the tumor is believed to be the causative factor responsible for the impaired renal tubular phosphate reabsorption, hypophosphatemia and osteomalacia." (PMID 28193220, 2017). "We have previously reported two male siblings with the first identified association between compound heterozygous mutations in FAM20C and FGF23 dependent hypophosphatemia in humans." (PMID 26543054, 2016). "Defects in FAM20C have been associated with a rare human disease, Raine syndrome/FGF23-related hypophosphatemia characterized by dental and bone hypomineralization." (PMID 27187611, 2016). "Tumors that overexpress FGF23 induce tumor-induced osteomalacia characterized by hypophosphatemia, which is caused by renal phosphate wasting." (PMID 26483756, 2015). "FGF-23 excess induces renal Pi wasting with resultant hypophosphatemia, 1,25 dihydroxyvitamin D (1,25(OH)2D) deficiency, rickets and osteomalacia." (PMID 26588476, 2015). "Human FGF23 was subsequently found to be a causative humoral protein for human tumor-induced osteomalacia characterized by hypophosphatemia caused by renal phosphate wasting." (PMID 26483756, 2015). "TIO is caused by (mesenchymal) tumors that produce FGF23 and consequently lead to hypophosphatemia and severely impaired bone mineralization." (PMID 26491212, 2015). "This scenario predisposes the patient to tertiary FGF-23 excess and altered mineral metabolism characterized by post-transplant hypophosphatemia." (PMID 24605319, 2014). "In Hyp mice, a murine model for X-linked hypophosphatemia (XLH), Phex deficiency results in the overproduction of FGF23 in osteocytes, which leads to hypophosphatemia and impaired vitamin D metabolism." (PMID 24710520, 2014). "As expected, intraperitoneal injection of 10 μg recombinant FGF23 (rFGF23) over 5 days into 3-month-old wild-type mice caused hyperphosphaturia and hypophosphatemia." (PMID 24797667, 2014). "Fam20c-deficient mice exhibit hypophosphatemia associated with the increased levels of Fgf23, and a loss-of-function mutation in the gene has been identified in patients who manifested hypophosphatemia." (PMID 24710520, 2014). "After kidney transplantation, nutritional vitamin D deficiency, persistent hyperparathyroidism, tertiary FGF-23 excess, hypophosphatemia, hypomagnesemia, immunosuppressive therapy, and alteration of sex hormones continue to impair bone health and growth." (PMID 24605319, 2014). "Increases in fibroblastic growth factor 23 (FGF23 or Fgf23) production by osteocytes result in hypophosphatemia and rickets in the Hyp mouse homologue of X-linked hypophosphatemia (XLH)." (PMID 25089825, 2014). "On the other hand, excess FGF23 causes hypophosphatemia, aberrant vitamin D metabolism and rickets/osteomalacia." (PMID 25089825, 2014). "Human genetic studies linking ENPP1 mutations to increased FGF23 levels and subsequent hypophosphatemia have recently been confirmed in an Enpp1−/− mouse model." (PMID 24906371, 2014). "Recently intravenous (iv) iron has been proposed to induce elevation of fibroblast growth factor 23 (FGF23), hypophosphatemia and osteomalacia in iron deficient subjects." (PMID 24373521, 2013). "Since FGF23 levels are highly regulated by serum phosphate or metabolic changes associated with hypophosphatemia, we can postulate that the resulting fall in phosphate levels as a consequence of iron-tubular toxicity would be expected to suppress FGF23 levels." (PMID 23902731, 2013). "For example, overproduction of FGF23 in osteoblastomas or stabilizing mutations in FGF23 protein is sufficient to cause hypophosphatemia, leading to osteomalacia or hypophosphatemic rickets in humans." (PMID 23451204, 2013).
hypophosphatemia (continued). "Here we report that pharmacological activation of FGFR1 with monoclonal anti-FGFR1 antibodies (R1MAb) in adult mice is sufficient to cause an elevation in serum FGF23 and mild hypophosphatemia." (PMID 23451204, 2013). "Mesenchymal tumors are seen in elderly and associated with FGF23 over-production and urine Pi wasting, hypophosphatemia, 1,25(OH)2D deficiency and osteomalacia." (PMID 23760058, 2013). "On the other hand, disorders that are caused by high circulating level of FGF23 are associated with hypophosphatemia while those corresponding to low circulating levels of FGF23 are associated with hyperphosphemia." (PMID 23455471, 2013). "Rare forms of FGF23 gain-of-function and loss-of-function mutations can cause familial forms of hyper- or hypophosphatemia, vitamin D alterations and soft-tissue injury." (PMID 23760058, 2013). "FGF23 hyperactivity and the resulting hypophosphatemia are associated with reduced bone density in tumor-induced osteomalacia and hereditary hypophosphatemic rickets." (PMID 23451204, 2013). "The prevention of osteomalacia is associated with substantially reduced serum Fgf23/hypophosphatemia, and less pronounced secondary hyperparathyroidism." (PMID 22629419, 2012). "We believe that a combination of cell differentiation failure and hypophosphatemia caused by the increase of serum FGF23 led to the skeletal defects in the Fam20c conditional knockout mice." (PMID 22615579, 2012). "Although DMP1 is expressed in both hard and soft tissues, the phenotype in human DMP1 mutations or Dmp1 deficient mice was mainly identified in the skeleton and the teeth, likely caused by hypophosphatemia, and increased FGF23 levels." (PMID 22879941, 2012). "Dmp1-, Phex- and Fam20c-deficient mice shared similarities in osteomalacia, hypophosphatemia and the remarkable elevation of FGF23 in the circulation and skeleton." (PMID 22615579, 2012). "The phenotypic changes in the Fam20c-conditional knockout mice share many similarities (hypomineralization, elevation of FGF23, hypophosphatemia) with those observed in the PHEX- and DMP1-deficient subjects." (PMID 22615579, 2012). "It is likely that a combination of cell differentiation failure and hypophosphatemia resulting from the FGF23 excess led to the skeletal defects in the Fam20c-deficient mice." (PMID 22615579, 2012). "Tumor-induced osteomalacia (TIO) is characterized by renal phosphate wasting, hypophosphatemia, and aberrant vitamin D3 metabolism and is caused by fibroblast growth factor 23 (FGF-23)–producing mesenchymal tumors, which are often difficult to locate." (PMID 21611969, 2011). "TIO is caused by tumoral increased production of FGF23, which predominantly operates at the proximal renal tubule to prevent the hydroxylation of 25-hydroxyvitamin D and phosphate reabsorption, which results in hypophosphatemia and, ultimately osteomalacia." (PMID 41438661, 2026). "However, FCM has been shown to raise serum fibroblast growth factor (FGF)-23 levels, causing hypophosphatemia and alterations in bone turnover in some patients." (PMID 41686372, 2026). "The underlying cause of hypophosphatemia following iron infusion relates to the carbohydrate moieties within IV iron preparations, which prevent the degradation/cleavage of FGF23, resulting in an increase in intact FGF23 levels." (PMID 41445555, 2025). "We diagnosed FGF23-related hypophosphatemic osteomalacia based on the following diagnostic criteria for osteomalacia: hypophosphatemia, elevated serum ALP levels, symptoms of bone pain, low bone mineral density, multiple uptakes in bone scintigraphy, and radiography findings of Looser zone." (PMID 39866919, 2025). "Moreover, conventional treatment increases FGF23 levels, potentially aggravating hypophosphatemia and 1,25(OH)2VitD deficiency." (PMID 40297189, 2025).
hypophosphatemia (continued). "The inhibition of FGF-23 activity with burosumab is associated with an increase in renal tubular phosphate reabsorption and the correction of hypophosphatemia in children with X-linked hypophosphatemia, which corresponds to a decrease in the severity of rickets." (PMID 40297189, 2025). "Moreover, other causes of FGF23-mediated hypophosphatemia share identical biochemical features of TIO and should be ruled out prior to making the diagnosis." (PMID 39755803, 2025). "In summary, FD is associated with FGF23 production and the development of hypophosphatemia." (PMID 40538772, 2025). "PMT cells excessively express FGF-23, which inhibits phosphate reabsorption in the renal tubules and the conversion of 25-hydroxyvitamin D to 1,25-dihydroxyvitamin D3, causing substantial phosphate loss in urine, leading to hypophosphatemia and osteomalacia." (PMID 39866529, 2025). "Additionally, FGF23-related hypophosphatemia has been closely associated with the development of spinal ligament ossification." (PMID 40535334, 2025). "In X-linked hypophosphatemia (XLH), PHEX gene variants lead to elevated FGF23 production, resulting in hypophosphatemia, osteomalacia, osteomalacia-related fractures, osteoarthritis, enthesopathy, spinal stenosis, and symptoms of pain, stiffness, and decreased physical function." (PMID 40314226, 2025). "Other syndromes can also be associated with FGF23-mediated hypophosphatemia, including fibrous dysplasia/McCune-Albright syndrome (FD/MAS), cutaneous skeletal hypophosphatemia syndrome (CSHS), neurofibromatosis type 1, osteoglophonic dysplasia, and Jansen’s metaphyseal chrondrodysplasia." (PMID 39755803, 2025). "Genetic causes of FGF23-mediated hypophosphatemia form an important consideration." (PMID 41445556, 2025). "Hypophosphatemia causes the downregulation of FGF23 and upregulation of 1,25(OH)2D3." (PMID 40661139, 2025). "Their inactivation causes overproduction of FGF23 and hypophosphatemia." (PMID 40649786, 2025). "Elevated FGF23 causes renal phosphate wasting and hypophosphatemia." (PMID 40661139, 2025). "However, Kassianides and Bhandari suggested a combination of calcitriol in conjunction with oral and parenteral phosphate supplementation to mitigate FGF-23-associated hypophosphatemia, as in the case of parenteral IIH." (PMID 39703298, 2024). "It should be noted that excessive activation of FGF23 may have detrimental effects on the body such as hypophosphatemia and bone loss." (PMID 38902808, 2024). "Hypophosphatemia is commonly associated with rickets, which is a defective condition of bone mineralization that occurs in children as a result of dysregulated phosphate transport and/or excessive serum FGF23 levels." (PMID 39482539, 2024). "Notably, studies have demonstrated that administering anti-FGF23 treatment can ameliorate hypophosphatemia and rickets in young mice with X-linked hypophosphatemia (XLH), while also increasing muscle strength and spontaneous motor activity in adult XLH mice." (PMID 39066929, 2024). "The young age of presentation, along with growth retardation and ear or dental abnormalities in the patient or their family members may hint toward genetic causes of osteomalacia associated with elevated FGF-23 and hypophosphatemia." (PMID 39055417, 2024). "However, the association between hypophosphatemia, ectopic FGF23 production and liver pathology has been more often documented in the context of chronic liver damage." (PMID 39525686, 2024). "FGF-23 is a polypeptide that reduces phosphate reabsorption and decreases the kidney's production of 1,25-dihydroxy vitamin D, resulting in urinary phosphate loss and hypophosphatemia." (PMID 39803160, 2024). "Animal studies have shown that iron deficiency induced by a low-iron diet stimulates Fgf23 transcription in bone, and suppresses intestinal phosphate absorption by downregulating the phosphate transporter NaPi2b in the duodenum, leading to hypophosphatemia." (PMID 39666728, 2024).